EGFR (epidermal growth factor receptor)
Diseases named in the same sentence as EGFR in open-access papers (continued):
Sharing a sentence is not in itself a finding about the gene and the disease.
osteoarthritis (20 papers, 2013 to 2025). A noninflammatory degenerative joint disease occurring chiefly in older persons, characterized by degeneration of the articular cartilage, hypertrophy of bone at the margins and changes in the synovial membrane. "Our study demonstrates for the first time anabolic effects in articular cartilage occurring in association with EGFR signal activation, and suggests novel possibilities for future application for cartilage repair and osteoarthritis treatment." (PMID 23705804, 2013). "Dermo1‐Cre; HB‐EGFf/f mice only showed a modest increase in bone mass, whereas Dermo1‐HB‐EGF mice developed progressive chondrodysplasia, chondroma, osteoarthritis‐like joint defects, and loss of bone mass and density, which were alleviated by treatment with EGFR inhibitor AG1478." (PMID 30550637, 2019). "Together these observations demonstrate effects of EGFR signaling in suppression of articular cartilage homeostasis, and suggest that activation of EGFR signaling may be a causal factor in osteoarthritis." (PMID 23705804, 2013). "Because estrogen protects articular cartilage and can limit the expression of phosphorylated epidermal growth factor receptor (p-EGFR) in the surface cartilage of the knee joint, it has a regulatory influence on osteoarthritis." (PMID 39618954, 2024). "Future investigation into the extent of bidirectional ER and EGFR cross-talk in chondrocytes and its influence on osteoarthritis would be justified." (PMID 36879303, 2023). "EGFR signaling is critical for maintaining adult cartilage homeostasis and attenuating osteoarthritis progression." (PMID 36187764, 2022). "In some contexts, inactivation of EGFR signaling has been shown to protect joints from surgically induced osteoarthritis, whereas in others, similar manipulations worsened joint pathology." (PMID 30828691, 2019). "Consistent with this, EGFR signaling is increased in the articular cartilage of osteoarthritic patients, and in rats following experimental surgical osteoarthritis induction." (PMID 23705804, 2013). "Accordingly, it was proposed that EGFR inhibitors could be repurposed for joint pain treatment, which was supported by several rodent studies with injury-induced osteoarthritis." (PMID 38004424, 2023). "The paradox of EGFR signaling in osteoarthritis may be explained by the dynamic function of this pathway during osteoarthritis progression." (PMID 36187764, 2022). "And we speculate that estrogen can inhibit the activation of cartilage EGFR signaling pathway by decreasing EGFR transcription in post-traumatic osteoarthritis progression." (PMID 35854298, 2022). "Signals from the epidermal growth factor receptor (EGFR) have typically been considered to provide catabolic activities in articular cartilage, and accordingly have been suggested to have a causal role in osteoarthritis progression." (PMID 23705804, 2013). "Therefore, EGFR has become a potential treatment target for Osteoarthritis." (PMID 38549939, 2024). "The current review summarizes recent studies of cartilage EGFR signaling in long bone development and diseases, provides potential explanations for the reported discrepancies, and suggests directions for future work to clarify the potential of this pathway as target for osteoarthritis treatment." (PMID 30828691, 2019). "We used deep machine learning algorithms, including the LASSO and SVM algorithms, to identify four candidate feature genes in Osteoarthritis cases: TK1, CD300A, EGFR, and UTY." (PMID 38549939, 2024). "Further data analysis validated that these genes (TK1, CD300A, EGFR, and UTY) are correlated with the immune microenvironment of Osteoarthritis." (PMID 38549939, 2024). "Deacetylating PTEN hinders the ubiquitination of epidermal growth factor receptor (EGFR), which strengthens extracellular matrix formation, triggers autophagy in chondrocytes, and offers defense against osteoarthritis." (PMID 38671436, 2024).
osteoarthritis (continued). "Previous studies in our lab have shown TGFα mediated activation of epidermal growth factor receptor (EGFR) induces cartilage degeneration in vitro, and inhibition of EGFR in vivo partially protects against surgically induced osteoarthritis in rats." (PMID 26562438, 2015). "Our results provide evidence that AREG acts through the EGFR and activates PI3K, Akt, and finally NF-kappaB on the MMP-13 promoter, thus contributing to cartilage destruction during osteoarthritis." (PMID 25147440, 2014). "However, EGFR activation by intra-articular administration of TGFα, rather than EGFR inhibition, was reported to attenuate osteoarthritis pain." (PMID 38004424, 2023). "Interestingly, a previous study has shown that AREG interacts with EGFR, activating PI3K/Akt, and subsequently inducing the NF-κB transcription factor interaction with the MMP-13 promoter, inducing cartilage destruction in osteoarthritis." (PMID 35841013, 2022). "Last but not least, Celecoxib prescription for pain relief in arthrosis could condition EGFR levels in the intestine of elderly patients already affected by different gut pathologies, possibly influencing the course of the disease and therapy." (PMID 25987127, 2015).
prostate adenocarcinoma (20 papers, 2010 to 2026). "The staining intensity associated with the EGFR protein expression was enhanced in 68% of 76 cases of primary prostatic adenocarcinoma specimens analyzed, as compared with the normal prostatic tissue from biopsy." (PMID 22384099, 2012). "Two study participants had partial response, one with neuroendocrine prostate cancer (NEPC) transformed from high-risk prostate adenocarcinoma and one with SCLC transformed from epidermal growth factor receptor (EGFR)-mutated NSCLC." (PMID 40160238, 2025). "We next examined EGFR mRNA expression in PCa tissues originating from the primary site (n = 495) using The Cancer Genome Atlas (TCGA) Prostate Adenocarcinoma Provisional database." (PMID 30134822, 2018). "Similarly, the epidermal growth factor receptor (EGFR) that is highly expressed in some prostate adenocarcinomas constituted an important target." (PMID 35164226, 2022). "Further, The Cancer Genome Atlas data (TCGA) independent database was used for validation of key genes EGFR, MYC, VEGFA, PTEN expression in prostate adenocarcinoma." (PMID 35456461, 2022). "More specifically, a positive immunoreactivity was observed for EGFR and its phosphorylated Tyr1173-pEGFR activated form, Ser473-pAkt and MIC-1 in the cytoplasm and near or at the cell surface in intermediate and luminal PC cells detected in prostatic adenocarcinoma specimens." (PMID 22384099, 2012).
folliculitis (19 papers, 2011 to 2024). Inflammation of the hair follicles. "In conclusion, folliculitis that develops more than four weeks after starting treatment with an EGFR inhibitor is typically caused by a staphylococcal infection." (PMID 36990917, 2023). "Folliculitis has drawn attention to cancer therapy associated skin toxicities and is common among patients treated with EGFR inhibitors (up to 100%)." (PMID 37925388, 2023). "The fundamental problem in terms of toxicity of the therapies that target the EGFR is the appearance of severe rash, infiltrated lymphocytes, folliculitis, and other adverse reactions that can cause in kidney cells and gastrointestinal mucosa." (PMID 37152586, 2023). "Anti-epidermal growth factor receptor (EGFR) therapy–associated cutaneous toxicity is a syndrome characterized by papulopustular rash, local inflammation, folliculitis, and microbial infection, resulting in a decrease in quality of life and dose interruption." (PMID 35324426, 2022). "For example, an epidermal growth factor receptor (EGFR) inhibitor such as gefitinib sometimes causes skin complications such as acneiform eruption, rash, or folliculitis." (PMID 36140200, 2022). "EGFR-antibodies are associated with significant skin toxicity, including acneiform rash and folliculitis." (PMID 30557370, 2018). "EGFR inhibitors are also known to cause folliculitis in up to 66.2% of treated patients." (PMID 38919203, 2024). "Furthermore, the chemoattractant activity of EGFR inhibitors causes neutrophil chemotaxis and leads to sterile folliculitis." (PMID 36708507, 2023). "According with other studies, ERL and AFT were mainly associated with the onset of infections such as folliculitis, the latter probably attributable to the implication of EGFR signaling pathway in hair cycle regulation and the maintenance of normal hair follicles." (PMID 36505840, 2022). "Despite that typical and EGFR inhibitor-induced folliculitis decalvans have different backgrounds, for both types of the disease, a similar therapeutic approach with antimicrobial and immunomodulating medications can be applied." (PMID 36708507, 2023). "Here, we review the literature cases of EGFR inhibitor-induced folliculitis decalvans and provide guidance on management and prevention of this condition in oncologic patients." (PMID 36708507, 2023). "Treatment of EGFR inhibitor-induced folliculitis decalvans frequently consists of oral tetracycline, topical steroids, and optional topical antibiotics." (PMID 36708507, 2023). "In the literature reported cases of folliculitis decalvans, the median time from the start of EGFR inhibitors to the first symptoms of alopecia was 4 months (range: 1–23 months)." (PMID 36708507, 2023). "Cutaneous toxicity induced by EGFR inhibitors (EGFRIs) is an inflammatory disorder characterized by papulopustular rash, folliculitis, microbial infection and pruritus." (PMID 35324426, 2022). "Given the folliculitis they can induce that can itself lead to alopecia, a potential protective effect of EGFR inhibitors towards alopecia is surprising." (PMID 23894460, 2013). "Histologically, the papulopustular skin rash of patients systemically treated with EGFR inhibitors for cancer often presents with neutrophil-rich suppurative folliculitis." (PMID 22761877, 2012). "Even though Nimotuzumab produces a downstream inhibition of the EGFR signaling pathway in normal skin cells, the characteristic lymphocytic infiltrates, folliculitis or perifolliculitis induced by other EGFR inhibitors have not been observed." (PMID 24212794, 2011). "In addition to the suppression of acute inflammation after UV exposure documented here, abrogation of EGFR function is also well known to lead to cutaneous inflammation, more specifically to folliculitis, in cancer patients undergoing longer-term treatment with EGFR inhibitors." (PMID 23878744, 2013).
folliculitis (continued). "Although the detailed mechanisms are not fully understood, it is anticipated that the strong inhibition of the EGFR/RTKs/PI3K/AKT/mTORC1 signaling pathways, which are involved in cell proliferation, is related to the development of folliculitis in both cases." (PMID 38919203, 2024). "Topical inhibition of signals downstream from EGFR, for example of pro-apoptotic pathways, may allow for protection from chemotherapy-induced alopecia without the folliculitis that results from EGFR inhibition." (PMID 23894460, 2013). "Intermittent inhibition could allow for folliculitis, a common side-effect of all EGFR-targeting agents, without providing protection from alopecia." (PMID 23894460, 2013).
metabolic syndrome (19 papers, 2012 to 2025). A cluster of metabolic risk factors for CARDIOVASCULAR DISEASES and TYPE 2 DIABETES MELLITUS. "In further investigation into the factors affecting EGFR-TKI-associated ILD revealed a significant correlation between ILD occurrence and concomitant dyslipidemia in patients treated with EGFR-TKI." (PMID 40949116, 2025). "PCB-180 uniquely impacts metabolic pathways, linking to metabolic syndrome, telomere shortening, and EGFR inhibition, promoting vascular stiffness and cellular aging." (PMID 40313580, 2025). "The analysis of the PCSF subnetwork showed that proteins associated with the EGFR and APOA1 pathways were generally decreased in serum samples collected from subjects with metabolic syndrome and MASLD at the end of 4-week DDDF compared with the serum collected before 4-week DDDF." (PMID 40551123, 2025). "The analysis of the PCSF subnetwork showed that proteins associated with the EGFR and APOA1 pathways were generally decreased in serum samples taken from subjects with metabolic syndrome and MASLD at the end of 4-week DDDF compared with the serum collected before 4-week DDDF." (PMID 40551123, 2025). "In addition, epidermal growth factor receptor (EGFR) stimulation has been identified as a therapeutic target for dyslipidemia and MASLD." (PMID 40722864, 2025). "The results indicated that quercetin had an excellent binding activity with many targets, including CCND1, HIF1A, MYC, AKT1, and EGFR; therefore, it might be a key compound for the effect against dyslipidemia." (PMID 35722157, 2022). "However, research on the interaction between EGFR-TKIs and dyslipidemia is limited, and whether a dose-effect relationship exists between the two remains unclear." (PMID 40949116, 2025). "Lastly, two potentially protective genes, EGFR and SOCS1, were identified with iHS, which suggests that these genes may be undergoing recent selective sweeps associated with the high prevalence of metabolic syndrome in modern humans." (PMID 27444955, 2016). "Those without metabolic syndrome tended to have a higher prevalence of gross total resection, methylguanine methyltransferase (MGMT) methylation, and epidermal growth factor receptor (EGFR) amplification." (PMID 39518104, 2024).
ameloblastoma (18 papers, 2011 to 2024). The most common odontogenic tumor, arising from the epithelial component of the embryonic tooth and usually affecting the molar-ramus region of the mandible or maxilla. "Remarkably, the unilocular to multilocular pattern rate was higher (1.3:1, 1.5:1, respectively) in the tumors with BRAF and multiple gene mutations, in contrast to SMO, NRAS, HRAS, and EGFR-mutated ameloblastomas (1:3, 1:2, respectively)." (PMID 29388014, 2018). "In conclusion, we describe EGFR nuclear localization in unicystic and multicyst ameloblastomas, in association with Cyclin D1 expression." (PMID 25991665, 2015). "Activation of EGFR can promote cell migration and invasion in ameloblastoma cells by enhancing MMP2 and MMP9 activity." (PMID 39100096, 2024). "Por otro lado, la patogénesis del ameloblastoma también se ha asociado con una hiperactividad del receptor del factor de crecimiento (EGFR) 50, lo que ocasiona un aumento en los niveles de ERK fosforilada y promueve la proliferación del tumor." (PMID 39444727, 2024). "Our group has previously shown that ameloblastoma cells expresses EGFR at a similar level to SCC cells." (PMID 36357495, 2022). "In conclusion, our data have shown that radiolabeled anti-EGFR antibody, 89Zr-panitumumab, can be used to effectively identify ameloblastoma tumor tissue in vivo." (PMID 36357495, 2022). "The aims of this study are to measure the specificity of radiolabeled 89Zr-panitumumab (an EGFR antibody) in vivo using patient-derived xenograft (PDX) models of ameloblastoma and positron emission tomography/computed tomography (PET/CT) scans." (PMID 36357495, 2022). "89Zr-panitumumab provides specificity to EGFR-expressing tumors, like ameloblastomas, and the ability to visualize tumors prior to surgery." (PMID 36357495, 2022). "This approach takes advantage of the EGFR expression seen in ameloblastoma tumors, while providing feasibility of utilizing advanced imaging for ameloblastoma detection." (PMID 36357495, 2022). "Our approach utilizes an immuno-PET agent, 89Zr-panitumumab, which binds to EGFR expressed by the ameloblastoma tissue." (PMID 36357495, 2022). "As a potential biomarker, the majority of ameloblastomas have been shown to be epidermal growth factor receptor (EGFR) positive." (PMID 36357495, 2022). "It has been shown that ameloblastomas are often characterized by overexpression of epidermal growth factor receptor (EGFR) and ERBB, as well as by mutations in SMO (smoothened), BRAF, and members of the MAPK pathways." (PMID 32155948, 2020). "Expression of EGFR was higher in the peripheral layer of ameloblastomas and the basal layer of dentigerous cysts." (PMID 33374329, 2020). "The confirmation of the direct binding of EGFR to the Cyclin D1 promoter in ameloblastomas can be further achieved by co-immunoprecipitation assay." (PMID 25991665, 2015). "We found that Cyclin D1 is co-localized with EGFR in unicystic and multicystic ameloblastomas, and the co-localization is clearer in the periphery of epithelial islands (ameloblast-like cells), which are cells that proliferate more." (PMID 25991665, 2015). "We show that, similar to other tumor types, there is nuclear EGFR in both, unicystic and multicystic, ameloblastomas." (PMID 25991665, 2015). "We aimed to assess EGFR nuclear localization in Ameloblastomas and to investigate if it colocalizes with nuclear Cyclin D1." (PMID 25991665, 2015). "We are describing the nuclear EGFR localization in ameloblastomas, however, future works with larger number of samples can reveal if this nuclear localization if of clinical significance." (PMID 25991665, 2015).